ALB (albumin)
Diseases named in the same sentence as ALB in open-access papers (continued):
Sharing a sentence is not in itself a finding about the gene and the disease.
malaria (continued). "FGA is a structural component of the extracellular matrix, while ALB is involved in oxygen binding; IL10 in African trypanosomiasis signaling and the malaria signaling pathway, and REN in the renin angiotensin system signaling pathway." (PMID 36762194, 2023). "In contrast, in a study on the general population and pregnant malaria patients, the activities of AST, ALP and total protein were elevated with a reduction in ALT, albumin and total bilirubin." (PMID 35219319, 2022). "First, bovine serum albumin (BSA) was selected as the model protein for nanoparticle loading and release tests due to the size similarity to the malaria antigens targeted in this study to obtain preliminary data." (PMID 36059505, 2022). "Only 9 (15%) severe malaria cases had mild or no acidosis, defined as a standard base deficit corrected for albumin SBDc ≤3.3 mmol/L." (PMID 30566600, 2019). "Since kwashiorkor patients seem to display an excess of prooxidants and as serum albumin is an important antioxidant, we hypothesized that patients with different forms of PEM might have different levels of malaria parasitaemia." (PMID 30533212, 2018). "Patients with severe falciparum malaria who had ethnicity of Thai or Myanmar, referred from other hospitals, no a prior history of malaria, and serum albumin <3.5 g/dL were more likely to require ICU admission." (PMID 23951178, 2013). "Children with malaria had decreased levels of apoA1 and albumin, but high levels of IL-10 when compared to children without malaria." (PMID 23208374, 2012). "A meta-analysis of 28 studies found that albumin levels were significantly lower in malaria patients compared with non-malarial controls (P < 0.001, standardized mean differences [SMD] = -2.23, 95% CI - 3.25 to - 1.20, I2: 98%, random effects model, 28 studies)." (PMID 38702420, 2024). "POC tests/WHO EDL for tier 1 facilities: This will include general IVDs for community and health settings without laboratories such as (Albumin, Bilirubin, Glucose, etc. and disease-specific IVDs for use in health settings without laboratories e.g. (Malaria, syphilis, HIV infection, etc." (PMID 36861922, 2023). "Although albumin too function as S1P acceptor, the observation of increased albumin in cerebrospinal fluid impairing BBB function of Malawian children with CM and reported S1PR1 internalization upon albumin-S1P binding precludes its utility in therapeutics use in malaria." (PMID 32923406, 2020). "Therefore, we hypothesized that the decreased level of S1P in malaria-infected mice with ALI/ARDS might be due to the concentration of S1P carrier proteins such as the low-density lipoprotein (LDL), high-density lipoprotein (HDL), and albumin fractions." (PMID 31483837, 2019). "There were mild liver impairment with or without mild renal impairment on day 0 however bilirubin, albumin, ALT, AST, creatinine, urea and electrolytes were gradually improved to normal limit by day 28 in malaria subjects treated with AN and DHP." (PMID 22554203, 2012).
venous thromboembolism (41 papers, 2017 to 2026). Occlusion of the lumen of a vein by a thrombus that has migrated from a distal site via the blood stream. "The serum albumin level appears to be the best marker of severity of NS and therefore a crucial predictor of the intensity of the prothrombotic state and venous thromboembolism risk." (PMID 39323731, 2024). "A serum albumin level <2.8 g/dl was the only predictor and was associated with 2.13-fold increased risk of venous thromboembolism." (PMID 39323731, 2024). "In a prospective cohort study, decreased serum albumin was associated with an increased risk of venous thromboembolism." (PMID 35571156, 2022). "Studies have also demonstrated an inverse relationship between serum albumin levels and risk of developing venous thromboembolism (VTE)." (PMID 33725003, 2021). "Background and Aim: Previous observational studies indicated that the serum albumin levels and circulating metabolites are associated with a high risk of venous thromboembolism (VTE)." (PMID 34859025, 2021). "Patients with higher albumin levels on admission had a 72% decreased risk of developing venous thromboembolism (adjusted relative risk [RR]:0.28, 95% confidence interval [CI]:0.14–0.53, p<0.001) for every 1 g/dL increase of albumin." (PMID 33725003, 2021). "Low levels of serum ALB have been found to be associated with different kinds of cardiovascular diseases, including venous thromboembolism, CHD, and incident ischemic heart disease." (PMID 33456482, 2020). "It has recently been shown in cancer patients that reduced serum albumin levels are significantly associated with an increased risk of venous thromboembolism (VTE) and mortality." (PMID 28800610, 2017). "Indeed, a recent study focused on venous thromboembolism events in female astronauts, showing an association between oral contraceptive use and serum albumin, among other factors, which potentially increase the risk of venous thromboembolism in astronauts." (PMID 40432927, 2025). "Therefore, in clinical practice, for patients with IMN and low serum albumin levels, we recommend oral anticoagulant therapy to prevent thrombosis, when necessary, based on their venous thromboembolism risk assessment results." (PMID 39981089, 2025). "Previous studies have shown that serum albumin was negatively correlated with vein thrombosis, and decreased albumin levels are associated with an increased risk of venous thromboembolism (VTE) in a linear dose-response manner; this association is independent of the inflammation influence." (PMID 36675764, 2023). "Also, low serum albumin was associated with increased risk of venous thromboembolism in several renal pathologies associated with proteinuria, although some studies have not found this association." (PMID 31936687, 2020). "A continuous analysis of albumin was used in only 15% of studies (2 of 13) evaluating complication outcomes, both of which were able to correlate albumin level with decreased risk of complications such as venous thromboembolism, pulmonary embolism, infection, and others." (PMID 40103850, 2025). "Albumin measurement has been used as a prognostic marker that may show a predisposition to venous thromboembolism due to increased fibrinolysis that may occur at peripheral ischemic sites, where clotting proteins may be part of the interim clot (e.g., in the lungs)." (PMID 36835858, 2023). "Low serum albumin, whose synthesis is stimulated by BCAA supplementation, has been associated with venous thromboembolism, major adverse cardiovascular events, and cardiovascular death." (PMID 41373420, 2025). "Low serum albumin is a signal of increased venous thromboembolism, which indicates a state of high inflammation or hyper-coagulation." (PMID 36432473, 2022). "Out of 37 variables, the most important factors in predicting both gastrointestinal leakage and venous thromboembolisms were age, height, and weight-related measures, hematocrit, albumin, and assistant training level." (PMID 35713855, 2022).
venous thromboembolism (continued). "Research indicates that serum albumin levels exhibit a linear negative correlation with the risk of venous thromboembolism and can predict short-term outcomes in APE." (PMID 41608662, 2026). "Therefore, they claimed that low albumin levels might contribute to frequently occurring venous thromboembolism." (PMID 35571156, 2022). "Therefore, low albumin levels, often present in cancer or critically ill patients, might contribute to the frequently occurring venous thromboembolism." (PMID 28800610, 2017).
Arrhythmia (40 papers, 2011 to 2025). Any cardiac rhythm other than the normal sinus rhythm. "In an older study, authors suggested that probucol-induced lengthening of the QTc and subsequent arrhythmias occurrence is linked to several risk factors, such as female sex, longer QTc before treatment and low serum albumin level." (PMID 37492082, 2023). "Results showed that coexisting arrhythmia, IMV usage and lower serum albumin values were significantly associated with lower survival probability of AECOPD patients." (PMID 38898420, 2024). "Lastly, some important variables influencing CKD outcomes (e.g. alcohol consumption habit, heart rate, arrhythmia, urine protein-to-creatinine or albumin to creatinine ratio, sodium, potassium, hematuria or renal ultrasonography) were lacking." (PMID 32728174, 2020). "In the final multivariable analysis, male sex, dysrhythmia, hemoglobin levels, albumin levels, and bis40map50_dur [odds ratio (OR), 1.26; P = .019] were associated with 90-day mortality." (PMID 32795266, 2020). "Coexisting arrhythmia, invasive mechanical ventilation (IMV) usage and lower serum albumin values were found to be significantly associated with lower survival probability of AECOPD patients, and these 3 predictors were further used to establish a prediction nomogram." (PMID 38898420, 2024). "However, admission for arrhythmia (OR 0.5, p=0.045), ACE inhibitor/angiotensin II receptor blockers use (OR 0.35, p=0.006), digoxin use (OR 0.4, p=0.013) and high albumin (OR 0.9, p=0.019) predicted lower 1-year all-cause mortality." (PMID 35641098, 2022). "There are many risk factors associated with postoperative anastomotic leakage, such as smoking, postoperative arrhythmia and other adverse cardiac events, the use of an Ivor-Lewis approach, advanced-stage cancer, lower preoperative albumin concentration, and so on." (PMID 33981719, 2021). "However, other factors, including electrolyte imbalances (potassium, calcium), liver function markers (bilirubin, INR, AST, albumin), and cardiac comorbidities (e.g., arrhythmia), also played a crucial role in enhancing the predictive accuracy of our statistical 12-parameter model." (PMID 40817221, 2025). "Using a case example of a patient with arrhythmia requiring IMV during hospitalization, with an admission serum albumin level of 30 g/L (vertical red lines)." (PMID 38898420, 2024). "The C-index of the nomogram based on age, arrhythmia, IMV, albumin, eosinophil, and leukocyte were 0.719 in the training cohort and 0.708 in the validation cohort." (PMID 38898420, 2024). "Coexisting arrhythmia, requiring IMV and serum albumin values were included to establish a predictive model for predicting of 7-day, 14-day and 21-day survival probability of AECOPD patients." (PMID 38898420, 2024). "We established a nomogram based on 3 predictors (coexisting arrhythmia, IMV usage and lower serum albumin values) for predicting the survival probability of AECOPD patients and the nomogram showed good performance." (PMID 38898420, 2024). "In multivariable analysis, category of surgical procedures, dysrhythmia, malignancy, ASA classification, hemoglobin levels and albumin levels were found to significantly predict 180-day mortality." (PMID 32795266, 2020). "Model 3 further adjusted for age, HTN, arrhythmia, CAD, HF, albumin (ALB), and prealbumin (PA)." (PMID 40266073, 2025). "Meanwhile, patients who experienced MACCE also showed a higher HR, respiratory rate, Killip class, occurrence of arrhythmia, and usage of IABP and ventilator, but lower blood pressure (both SBP and DBP), albumin level, total triglyceride level, and LVEF than those who did not experience MACCE." (PMID 37061678, 2023). "In contrast, arrhythmia, other diseases, FEV1, mean corpuscular volume, BMI, mean corpuscular hemoglobin concentration, albumin, C reactive protein, smoking duration, hematocrit, aspartate aminotransferase, percentage VC, and duration of smoking cessation were unlikely to predict rapid decliners." (PMID 37012340, 2023).
co-infection (40 papers, 2006 to 2026). "The application of mechanical ventilation, decreased serum albumin, co-infection with aspergillosis or CMV, and underlying chronic pulmonary disease are reported as poor prognostic factors for PJP patients." (PMID 36552932, 2022). "Results of the present study showed that HIV/HBV co-infection was significantly associated with increase in total protein and decrease in albumin." (PMID 36032489, 2022). "The analysis revealed that HIV-helminth coinfection was associated with patterns of lower prealbumin and albumin levels across all BMI categories in the subgroup with normal CRP except in the obese, although not statistically significant." (PMID 30065944, 2018). "Results from univariate analysis revealed that respiratory rates ≥ 30 breaths/min at admission, and decreased baseline blood lymphocytes, blood albumin, PaO2/FiO2 and coinfection were associated with an increased risk for 30-day mortality in IC patients with Flu-p." (PMID 34429126, 2021). "Human albumin use: only the fungal infection group had a significantly higher frequency (21%, P < 0.001) vs. the non-co-infection group (8.7%)." (PMID 41355981, 2025). "Low albumin levels, high WBC counts, poor glycemic control, co-infection, and higher levels of acidosis were risk factors of ESS in DK/DKA patients." (PMID 37700304, 2023). "The study assessed the impact of HIV and HBV mono- and co-infections on serum total protein, albumin, globulin fractions and plasma free amino acids concentrations." (PMID 36032489, 2022). "Our study showed overall lower values of albumin in all serotypes of infection, but in cases of co-infection, hypoproteinemia was more evident." (PMID 34136322, 2021). "Cases with co-infection had a much higher derangement of liver function and lower mean serum albumin than infections with a single serotype." (PMID 34136322, 2021). "Similar results were confirmed in a study conducted in Singapore amongst patients with TB and HIV co-infection, where a mean albumin value of 29.6 g/ dL was reported." (PMID 34394968, 2021). "HIV coinfection, bodyweight, GCS, albumin, AST, ALT, and MRC grade were associated with death (P < 0.01) by univariate analysis; with correlations (r > 0.69) between AST and ALT, GCS, and MRC." (PMID 31956998, 2020). "Recently, the importance of Albumin levels and weights were underlined as an unsuccessful outcome in TB-HIV co-infection." (PMID 30181996, 2018). "Univariate logistic regression identified TB co-infection, low Karnofsky score, high aspartate aminotransferase, low albumin levels, high 4β-hydroxycholesterol to cholesterol ratio, and high HIV viral load as significant predictors of SVDD at baseline." (PMID 27559961, 2016). "A reason for the increased levels of the albumin in HBV-S.typhi co-infection could be attributed to the liver’s response to the free radicals generated by S. typhi in chronicity, to provide an antioxidative function, since albumin is a metabolic antioxidant." (PMID 40911532, 2025). "The analysis of liver’s function of protein synthesis—based on the mean serum albumin values—exhibited the lowest albumin levels in HBV/HDV co-infection (4.27 g/dL), and the highest in the HCV single infection (4.86 g/dL), with a highly significant difference between them (p-value = 0.0474)." (PMID 40558579, 2025). "Interestingly, despite higher lung inflammatory scores at 48 hours post co-infection, albumin levels were reduced." (PMID 40788118, 2025). "Increased blood concentrations of total protein, globulin fractions, essential and non-essential amino acid profiles, and observed reduction in serum albumin concentration may be associated with HIV and HBV co-infection." (PMID 36032489, 2022). "In addition, the low blood albumin level (32±4 g/L vs. 27±4 g/L, P = 0.030) and co-infection with aspergillus (4% vs. 27%, P = 0.011) were also associated with poor prognosis." (PMID 26422246, 2015).
co-infection (continued). "Subsequently, we obtained the top 16 hub targets of probenecid for SARS-CoV-2/RSV co-infection, namely, AKT1, ALB, EGFR, CASP3, CTNNB1, SRC, HSP90AA1, and so on." (PMID 40371107, 2025). "Co-infection with HCV/HIV patients indicated had a larger margin of decrease in ALAT (16.1733 IU/L), ASAT (23.0274 IU/L), albumin (2.0833 mg/dL) and total bilirubin (18.1818 mg/dL) compared with mono-infected patients." (PMID 34449737, 2021). "We compared HCV RNA and liver enzyme (ALT, AST, albumin, bilirubin, GGT, AFP) levels in acute, HCV mono-infection, and HIV-HCV coinfection." (PMID 30865664, 2019). "Multivariate logistic regression, using a backward stepwise conditional model of all variables with a P value <0.1 in the univariate analysis, identified TB co-infection, high HIV viral load, and low albumin level as significant predictors of SVDD at baseline." (PMID 27559961, 2016). "The HBV-HCV co-infection group had higher ALT, AST, ALP, GGT, APRI and FIB-4 levels, but lower ALB and total platelet compared to the HBV mono-infection group." (PMID 26422607, 2015). "The HBV-HCV co-infection group had higher ALT, AST, ALP, GGT, APRI and FIB-4 levels, but lower ALB and total platelet compared to the HBV mono-infection group, and similar to that of the HCV mono-infected group." (PMID 26422607, 2015). "It was found that the level of albumin (ALB) was significantly lower in patients with co-infection than in those without co-infection (P=0.001)." (PMID 38106473, 2023). "By contrast, single infection with P. chabaudi led to a transient and mild increase in intestinal albumin levels on 7 dpi, and this was not exacerbated by co-infection." (PMID 33440153, 2021). "Both groups with co-infection had a higher mean neutrophil percentage, platelet count, AST, and ALT than the no co-infection group and lower lymphocyte percentage and albumin than the no co-infection group." (PMID 34136322, 2021). "The albumin to globulin (A/G), triglyceride (TG), cholesterol, low-density lipoprotein (LDL), white blood cell (WBC), and PLT levels were higher in the mono-infection group than in the co-infection group." (PMID 32678224, 2020). "However, IAV infection alone caused significant vascular injury, as indicated by increased albumin levels in BALF, while co-infection with Af did not further exacerbate vascular leakage." (PMID 40788118, 2025).